CRISP1 (cysteine rich secretory protein 1)
Description:
May have a role in sperm-egg fusion and maturation.
Synonyms: CRISP-1; AEGL1; ARP; HUMARP; HSCRISP1D; HSCRISP1G; HEL-S-57
Tractability: Antibody: UniProt predicts a signal peptide or a membrane-spanning region; its Gene Ontology location is reachable by antibodies, with medium confidence.
Gene: Protein-coding gene on chromosome 6 (49,834,257 to 49,877,096, reverse strand). Ensembl gene ENSG00000124812.
Gene Ontology:
Biological process: fusion of sperm to egg plasma membrane involved in single fertilization
Cellular component: nucleus; extracellular region
Genetic constraint (gnomAD): Loss-of-function variants: 33 observed, 25.19 expected, observed/expected ratio (o/e) 1.31, 90% interval 0.99 to 1.74. The upper end of that interval is the gene's LOEUF score, 1.74, which puts it in group 6 of 6, group 1 being the genes least tolerant of losing a copy. Missense variants: 320 observed, 263.82 expected, observed/expected ratio (o/e) 1.21, 90% interval 1.11 to 1.33. Synonymous variants: 94 observed, 90.53 expected, observed/expected ratio (o/e) 1.04, 90% interval 0.88 to 1.23.
Homologues: Orthologues: chimpanzee CRISP1 (99% identical), macaque CRISP1 (85% identical), rat Crisp1 (63% identical), pig CRISP1 (62% identical), mouse Crisp4 (61% identical), rabbit CRISP1 (61% identical), zebrafish glipr1a (24% identical), Caenorhabditis elegans scl-14 (22% identical), Caenorhabditis elegans scl-5 (22% identical), Caenorhabditis elegans scl-7 (22% identical), Drosophila melanogaster CG42564 (22% identical), Caenorhabditis elegans scl-10 (21% identical), and 40 more. Paralogues in human: CRISP2 (43% identical), CRISP3 (42% identical), CLEC18A (31% identical), CLEC18C (30% identical), CLEC18B (30% identical), CRISPLD2 (30% identical), CRISPLD1 (29% identical), GLIPR1 (29% identical), PI15 (26% identical), GLIPR1L2 (25% identical), R3HDML (23% identical), GLIPR1L1 (22% identical), and 1 more.
Diseases named in the same sentence as CRISP1 in open-access papers:
CRISP1 is named in the same sentence as 7 diseases in open-access papers, as found by Europe PMC text mining. Sharing a sentence is not in itself a finding about the gene and the disease. The quoted sentences say what the papers report.
alopecia areata (1 paper, 2024). Loss of scalp and body hair involving microscopically inflammatory patchy areas. "Crisp1 (Cysteine-rich secretory protein 1): The mouse strain C3H/HeJ, which is prone to alopecia areata, is deficient in Crisp1 protein in the hair shaft." (PMID 38790256, 2024). "Although clinically C3H/HeJ mice have normal hair, abnormal Crisp1 expression may predispose them to alopecia areata and affect the severity of the disease." (PMID 38790256, 2024).
Infertility (1 paper, 2022). "The deletion of C11orf94 leads to infertility in mice by affecting the expression of calcium pathway related proteins such as PDE1C, LGMN and ADD1, as well as sperm-oocyte fusion related proteins such as CRISP1, IZUMO1 and EQTN in mouse sperm." (PMID 36050562, 2022).
cancer (2 papers, 2017 to 2025). A tumor composed of atypical neoplastic, often pleomorphic cells that invade other tissues. "These genes were presumably involved in cancer (SMG6, HCK), cellular growth (CPVL), reproduction (ADGB, CRISP1, CTTNBP2NL, WDR78), and nervous system (AUTS2, CNTNAP2, CPVL, SRGAP2)." (PMID 40149444, 2025).
tumor (1 paper, 2014). "In our analysis from tumor versus “normal” germline samples, expression data demonstrated significant (p≤ 2.0-fold) down-regulation of LNX2 and FGD6 and up-regulation of CRISP1 in LGG." (PMID 25153720, 2014).
CRISP1 also shares sentences with these, for which no sentence is quoted: Azoospermia (2 papers); epididymitis (1); inflammatory skin disease (1).